METTL3 (methyltransferase 3, N6-adenosine-methyltransferase complex catalytic subunit)
Diseases named in the same sentence as METTL3 in open-access papers (continued):
Sharing a sentence is not in itself a finding about the gene and the disease.
hepatocellular carcinoma (continued). "Similarly, an increased expression of METTL3 has been reported in hepatocellular carcinoma (HCC) patients, as well as in in vivo experiments." (PMID 39457524, 2024). "For instance, it's been reported that METTL3 partners with YTHDF1 to boost hepatocellular carcinoma progression, triggers the PI3K/AKT signaling pathway to enhance prostate cancer growth, and plays roles in chemoresistance across various cancers like oral cancer, acute myeloid leukemia, and more." (PMID 38112021, 2023). "Another study in hepatocellular carcinoma (HCC) cells found that METTL3 promoted proliferation by inhibiting the expression of SOCS2, a transcription factor that can negatively regulate cell proliferation, through m6A-dependent/YTHDF2-mediated mRNA degradation." (PMID 35350378, 2022). "In sorafenib-resistant hepatocellular carcinoma, METTL3 was significantly down-regulated and could promote m6A modification of FOXO3 3’UTR increasing its stability via recruiting YTHDF1, thereby enhancing sorafenib resistance of HCC." (PMID 35144642, 2022). "METTL3 is significantly upregulated in hepatocellular carcinoma and promotes tumor progression." (PMID 36406135, 2022). "METTL3 could also drive hepatocellular carcinoma progression by mediating m6A modification of ubiquitin-specific processing protease 7 (USP7) or abnormal spindle-like microcephaly (ASPM)." (PMID 36476503, 2022). "Moreover, of the m6A modulators, METTL3 is a key component of the m6A methylation complex and is reportedly involved in hepatocellular carcinoma, breast cancer, and colon cancer." (PMID 35096816, 2021). "On the contrary, METTL3 was up-regulated in human hepatocellular carcinoma and lung cancer." (PMID 34149801, 2021). "Moreover, METTL3 expression was found to be significantly upregulated in other types of cancer, such as hepatocellular carcinoma (HCC) and cholangiocarcinoma." (PMID 34094960, 2021). "Studies have shown that YTHDC2 and METTL3 can promote the development of hepatocellular carcinoma." (PMID 34055974, 2021). "Chen et al22 reported that the functional expression of METTL3 could contribute to the progression of hepatocellular cancer development." (PMID 33090698, 2020). "It is worth noting that this study demonstrates that overexpression of miR‐24‐2 in human hepatoma cell line Hep3B promotes the expression of N6‐adenine methyltransferase METTL3 and thereby increases methylation modification (m6A) on N6‐adenosine from specific RNA." (PMID 32030886, 2020). "As a reversible epi-transcriptome modulator, methyltransferase-like 3 (METTL3) is a key member of the m6A methyltransferase complex, and has recently been reported to be essential for tumor progression in leukemia, hepatocellular carcinoma, and malignant glioma via diverse downstream genes." (PMID 31230592, 2019). "Moreover, one study showed that high m6A modification promoted hepatocellular carcinoma progression which was ascribed to high METTL3 expression, while another study believed that was ascribed to low METTL14 expression." (PMID 31230592, 2019). "Despite the significance of METTL3 in hepatocellular carcinoma (HCC), its post-translational modifications and their functional implications in HCC remain poorly understood." (PMID 40651967, 2025). "In hepatocellular carcinoma (HCC), METTL3 suppresses SOCS2 expression in a YTHDF2-dependent manner, while WTAP reduces ETS1 mRNA levels through the m6A mechanism, collectively promoting cell cycle progression and tumor proliferation." (PMID 41446042, 2025). "METTL3, the principal RNA N6-adenosine methyltransferase, is significantly elevated in human hepatocellular carcinoma (HCC) and various solid tumors, correlating with adverse outcomes in patients with HCC." (PMID 39791162, 2025). "Long non-coding RNA TUG1 is highly expressed in hepatocellular carcinoma (HCC), driven by METTL3-mediated m6A modification." (PMID 41346602, 2025).
hepatocellular carcinoma (continued). "In HCC, METTL3 and METTL14 have opposing effects on the migration of hepatocellular carcinoma cells." (PMID 38166703, 2024). "The overexpression of METTL3 in hepatocellular carcinoma (HCC) leads to the degradation of the oncogene SOCS2 through m6A modification, which is associated with poor patient prognosis." (PMID 38649363, 2024). "In hepatocellular carcinoma (HCC), METTL3-mediated m6A modification stabilizes lncRNA LINC00958 to promote HCC progression." (PMID 37404673, 2023). "Genes related to the m6A modification, such as METTL3 and YTHDF1, are upregulated in hepatocellular carcinoma (HCC) and associated with a worse prognosis." (PMID 36768585, 2023). "In hepatocellular carcinoma (HCC) cells, the depletion of METTL3 can promote autophagy by inducing autophagy-related gene transcription and leading to forkhead box protein O3 (FOXO3) degradation via a YTHDF1-dependent pathway." (PMID 36632456, 2023). "For example, METTL1 has been shown to act as an oncogene in bladder cancer, hepatocellular carcinoma (HCC), acute myeloid leukemia, and intrahepatic cholangiocarcinoma; the METTL3/14 complex acts as a tumor suppressor in thyroid and endometrial cancers." (PMID 36830565, 2023). "For instance, previous reports showed that METTL3 expression was significantly higher in hepatocellular carcinoma (HCC) than normal controls and it was correlated with shorter recurrence-free survival and overall survival." (PMID 35280730, 2022). "In hepatocellular carcinoma (HCC), METTL3 has been shown to play a protumorigenic role by decreasing the level of RDM1, a key regulator of the DNA double-strand break repair and recombination, RNA processing and protein translation." (PMID 33814008, 2021). "The present review focuses on hepatocellular carcinoma, and demonstrates several potential targets of METTL3 and the way METTL3 contributes to HCC in a m6A-dependent manner." (PMID 34046411, 2021). "In hepatocellular carcinoma (HCC), METTL3 enhances the degradation of m6A-containing SOCS2 mRNA together with YTHDF2." (PMID 32303268, 2020). "Here, we find that METTL3, a primary m6A methyltransferase, is significantly down‐regulated in human sorafenib‐resistant hepatocellular carcinoma (HCC)." (PMID 32368828, 2020). "In human hepatocellular carcinoma (HCC), highly expressed METTL3 restrains expression of SOCS2 via YTHDF2-mediated degradation." (PMID 31801551, 2019). "In hepatocellular carcinoma (HCC), METTL3 is significantly upregulated and indicates poor prognosis." (PMID 31921664, 2019). "In hepatocellular carcinoma, METTL16 and METTL3 collaborate to enhance m6A modifications on ZNF706 neighboring transcript 1 (ZNNT1) mRNA, thereby increasing its stability and expression." (PMID 41459114, 2026). "Methyltransferase like 3 (METTL3), an m6A “writer,” is upregulated in lenvatinib-resistant hepatocellular carcinoma, enhancing EGFR mRNA translation and activating ERK signaling." (PMID 41247642, 2025). "Tumor-intrinsic METTL3 suppresses CD8+ T cell activation and effector functions, thereby driving immune evasion and non-alcoholic fatty liver disease related hepatocellular carcinoma progression." (PMID 40986143, 2025). "O-GlcNAc modification reduces METTL3 ubiquitination, thereby increasing protein stability, and enhances its interaction with WTAP, thereby sustaining m6A levels in hepatoma cells." (PMID 40651967, 2025). "METTL3 enhances the stability of the long non-coding RNA (lncRNA) LINC00958, which promotes lipogenesis in hepatocellular carcinoma (HCC)." (PMID 40428320, 2025). "For example, in hepatocellular carcinoma, high expression of METTL3 was positively correlated with G6PD expression, and patients with low expression of METTL3 and high expression of G6PD had a relatively better prognosis." (PMID 40458727, 2025).
hepatocellular carcinoma (continued). "In hepatocellular carcinoma (HCC), METTL3 has been reported to promote tumor cell proliferation through the YTHDF2-dependent silencing of SOCS2, resulting in the overactivation of the JAK/STAT pathway." (PMID 40136363, 2025). "A recent study on hepatocellular carcinoma (HCC) found that ferroptosis is regulated by the PPARGC1A/BAMBI/ACSL5 axis, with METTL3 and WTAP inhibiting PPARGC1A in an m6A- and YTHDF2-dependent manner." (PMID 40271153, 2025). "Also, in hepatocellular carcinoma (HCC), METTL3 stabilizes LINC00958, Snail, and CTNNB1, thereby contributing to cellular processes such as lipogenesis, proliferation, metastasis, and tumor growth." (PMID 38966069, 2024). "For example, Methyltransferase METTL3 directly mediates the m6A modification of LNCC00958 to enhance its stability, and then promotes the progression of hepatocellular carcinoma by up-regulating the expression of HDGF." (PMID 38180752, 2024). "METTL3 also enhances the expression and stability of LINC00958, which targets miR-3619-5p to upregulate hepatocellular carcinoma-derived growth factors, thereby promoting HCC lipogenesis and progression." (PMID 38921460, 2024). "In primary hepatocellular carcinoma (HCC), METTL3 adds m6A modification to the 3′-UTR of FOXO3 mRNA, a negative regulator of autophagy, increasing its mRNA stability in a YTHDF1-dependent manner." (PMID 39686999, 2024). "In hepatocellular carcinoma (HCC), METTL3 adds m6A methylation marks to the coding sequence (CDS) and 3′untranslated region (UTR) of key EMT transcription factor Snail, thereby enhancing its translation process." (PMID 39473440, 2024). "Research on METTL3, ALKBH5, hepatocellular carcinoma, plant viruses, cancer progression, and Type I interferonthe current focal point and anticipated trend for future investigations." (PMID 38238848, 2024). "In hepatocellular carcinoma (HCC), METTL3 seems to have adouble-facedrole." (PMID 36692498, 2023). "In hepatocellular carcinoma (HCC) patients, METTL3 overexpression correlated with poor prognosis." (PMID 37612540, 2023). "In hepatocellular carcinoma (HCC), METTL3 was SUMOylated by a small ubiquitin-like modifier SUMO1, which in turn facilitated the oncogenic function of METTL3." (PMID 36009465, 2022). "Another study showed that METTL3 catalyzes m6A modification of FEN1 mRNA, which is recognized and stabilized by IGF2BP2 in hepatocellular carcinoma cells." (PMID 35502895, 2022). "A previous study found that the overexpression of METTL3 in hepatocellular carcinoma (HCC) may promote the degradation of the SOCS2 gene, resulting in an abnormal JAK/STAT signaling pathway, causing the proliferation and migration of HCC cells." (PMID 36230944, 2022). "More detailed studies are needed, however, to characterize METTL3 and METTL14 in glioblastoma and hepatocellular carcinoma." (PMID 36360287, 2022). "In hepatocellular carcinoma (HCC), METTL3 depletion promoted the LC3-II accumulation by reducing the stability of FOXO3 mRNA through a YTHDF1-dependent mechanism." (PMID 36517820, 2022). "In hepatocellular carcinoma (HCC), the upregulation of METTL3 and downregulation of METTL14 may contribute to HCC progression and metastasis, causing a poor prognosis of patients." (PMID 36051357, 2022). "In patients with HCC, overexpression of METTL3 can reduce the expression of RDM1 in an m6A-dependent manner, promoting the survival, proliferation, and stability of hepatocellular carcinoma cells." (PMID 36230944, 2022). "In hepatocellular carcinoma (HCC), METTL3 expression positively correlated with glycolysis genes SLC2A1, HK2, PFKM and PKM." (PMID 33669361, 2021). "In hepatocellular carcinoma (HCC), silencing METTL3 and METTL14 has been shown to reduce the level of circRNA-SORE, which acts as a miRNA sponge by recruiting miR-103a-2-5p and miR-660-3p to competitively activate the Wnt/β-catenin pathway, thereby inducing sorafenib resistance." (PMID 34315512, 2021).
hepatocellular carcinoma (continued). "In hepatocellular carcinoma (HCC), METTL3 has been found to upregulate in cancerous cells compared to normal hepatocytes." (PMID 33814008, 2021). "In hepatocellular carcinoma (HCC), METTL3-mediated increase in the m6A level of SOCS2 mRNA promotes degradation of this ubiquitous cytokine signaling transducer through an m6A YTHDF2-dependent mechanism; the decreased expression of SOCS2 promotes HCC progression." (PMID 34105069, 2021). "In human hepatocellular carcinoma (HCC), METTL3 was found to be significantly upregulated and contributed to the poor prognosis of HCC patients." (PMID 32429972, 2020). "In hepatocellular carcinoma, METTL14 antagonizes METTL3 by suppressing tumor metastasis via interaction with DGCR8." (PMID 32709063, 2020). "In hepatocellular carcinoma (HCC), METTL3-mediated m6A modification enhances the stability of LINC00958 transcript, which can upregulate hepatoma-derived growth factor (HDGF) expression by sponging miR-3619-5p to promote tumor growth." (PMID 33292652, 2020). "The m6A writer METTL3 was reported to upregulate in hepatocellular carcinoma (HCC)." (PMID 32194861, 2020). "In human hepatocellular carcinoma (HCC), METTL3 has been elucidated to be frequently upregulated and contributes to HCC progression through a distinct mechanism." (PMID 29587823, 2018). "Moreover, we demonstrated that O-GlcNAcylation significantly increases METTL3 stability and binding to WTAP, leading to elevated m6A levels in hepatoma cells." (PMID 40651967, 2025). "In non-alcoholic fatty liver disease-hepatocellular carcinoma (NAFLD-HCC), METTL3 enhances m6A methylation on the mRNA of sterol regulatory element-binding protein (SREBP) cleavage-activating protein (SCAP), promoting its translation and activating cholesterol biosynthesis." (PMID 39987091, 2025). "Although O-GlcNAcylation of METTL3 had minimal effect on its subcellular localization and methyltransferase activity, it enhanced its interaction with WTAP, thereby sustaining m6A levels in hepatoma cells and stabilizing MCM10 mRNA via IGF2BP3." (PMID 40651967, 2025). "CCK-8 and colony formation assays revealed that METTL3 knockdown significantly inhibited hepatoma cell proliferation, and this effect was reversed by the reintroduction of METTL3-WT, but not METTL3-3A." (PMID 40651967, 2025). "METTL3 and ubiquitin specific peptidase 7 (USP7) expressions were interrelated in hepatocellular carcinoma cells and conclusive remarks obtained were that maybe METTL3 can regulate the USP7 expression by m6A methylation." (PMID 39691424, 2024). "The result showed that topics such as METTL3, ALKBH5, hepatocellular carcinoma, plant viruses, cancer progression, clinical application, and IFN-1 reflect good development trends and may be future research hotspots." (PMID 38238848, 2024). "METTL3 regulation is also involved in glycolysis metabolism in hepatocellular carcinoma, esophageal squamous cell carcinoma, and non-small cell lung cancer." (PMID 36476503, 2022). "For example, METTL3-mediated m6A methylation modification, resulting in LINC00958 upregulation by stabilizing its RNA transcript and the high level of LINC00958, led to the poor overall survival of hepatocellular carcinoma patients." (PMID 35562992, 2022). "For instance, upregulation of hepatitis B virus X-interacting protein (HBXIP) positively promotes expression of the m6A methylase METTL3, resulting in enhanced HIF-1α expression and maintenance of high levels of glycolysis, thus promoting malignant proliferation of hepatocellular carcinoma (HCC)." (PMID 35794625, 2022). "Similarly, METTL3-mediated m6A methylation modification can up-regulate LINC00958, resulting in low overall survival in patients with hepatocellular carcinoma." (PMID 36429081, 2022). "In hepatocellular carcinoma, reduced METTL14 expression, but not METTL3 was associated with adverse patient prognosis and tumor metastasis by regulating the process of pri-miR126." (PMID 33430867, 2021).
hepatocellular carcinoma (continued). "METTL3 directed m6A modification of tumor suppressor gene SOCS2 and silenced its expression depending on YTHDF2-mediated degradation pathway, which promoted the progression of hepatocellular cancer." (PMID 34149801, 2021). "In particular, METTL3-mediated m6A modification was found to stabilize the lncRNA LINC00958 transcript to increase the expression of the hepatoma-derived growth factor, ultimately facilitating the growth of hepatocellular carcinoma." (PMID 34802433, 2021). "Additionally, METTL3 was found to have dramatical overexpression in hepatocellular carcinoma (HCC), and the depletion of METTL3 contributed to the significant suppression of the HCC growth and metastasis." (PMID 35003212, 2021). "Patients in the low METTL3/YTHDF1 group have a better prognosis, so the combination of METTL3 and YTHDF1 serves as a biomarker reflecting the malignancy and prognostic outcome of hepatocellular carcinoma." (PMID 34660577, 2021). "The observation of similar effects after manipulating METTL3 and YTHDF2 expression supports the concept that the axis consisting of m6A writer and m6A reader is likely to exist in BCa, analogous to a previous study in hepatocellular carcinoma." (PMID 32126149, 2020). "METTL3 mediates m6A modification of lnc-TSPAN12 to drive migration and invasion of hepatocellular carcinoma(HCC) cells, which in turn promotes hepatic metastasis." (PMID 41256854, 2025). "CPP-M2, not CPP-M1, significantly attenuated METTL3 O-GlcNAcylation in hepatoma cells." (PMID 40651967, 2025). "Recent studies have revealed that methyltransferase-like 3 (METTL3), a pivotal RNA N6-adenosyl methyltransferase, exhibits substantial upregulation in human hepatocellular carcinoma (HCC) and multiple solid tumors." (PMID 40600050, 2025). "For instance, in hepatocellular carcinoma, METTL3 stabilizes FOXO3 in a m6A-dependent manner, inhibiting autophagy and increasing the sensitivity of HCC to sorafenib." (PMID 38576024, 2024). "Current research has illuminated the pivotal role of RNA m6A methyltransferase complex components, particularly METTL3 and METTL14, in the pathogenesis and progression of cancers, including acute myeloid leukemia (AML) and hepatocellular carcinoma (HCC)." (PMID 39329012, 2024). "YTHDF2 has also been shown to induce METTL3‐mediated suppressor of cytokine signaling 2 (SOCS2) mRNA degradation in hepatocellular carcinoma (HCC), therefore driving HCC cell proliferation, migration, and colony formation." (PMID 38721006, 2024). "In hepatocellular carcinoma (HCC), the cancer-testis lncRNA-CTHCC promotes HCC growth and metastasis, and mechanistically, lncRNA-CTHCC is modified by m6A methylation with METTL3 and IGF2BP1/IGF2BP3 to maintain its stability and increase its expression." (PMID 35541906, 2022). "In addition, METTL3 may regulate the expression of USP7 through modification of m6A methylation and may promote the invasion of hepatocellular carcinoma cells." (PMID 36230944, 2022). "For example, METTL3 synergizes with hepatitis B X-interacting protein (HBXIP) to regulate the abundance of m6A modification of hypoxia-inducible factor-1 alpha (HIF-1α), resulting in metabolic reprogramming and malignant progression of hepatocellular carcinoma cells." (PMID 36476503, 2022). "A recent report demonstrated that deletion of METTL3 impairs m6A and weakens the migration, invasion and EMT of hepatocellular carcinoma (HCC) cells in vitro and in vivo." (PMID 34211849, 2021). "However, METTL3 and METTL14 play opposite regulatory roles in hepatocellular carcinoma (HCC)." (PMID 33159022, 2020). "For instance, METTL3 acts as a promoter of ferroptosis in esophageal squamous cell carcinoma (ESCC), while WTAP suppresses ferroptosis in hepatocellular carcinoma (HCC)." (PMID 40271153, 2025).